TGFB1 (transforming growth factor beta 1)
Diseases named in the same sentence as TGFB1 in open-access papers (continued):
Sharing a sentence is not in itself a finding about the gene and the disease.
tumor (continued). "However, as a natural response to the hypoxic and inflammatory conditions that occur during tumor progression, high production levels of TGFβ1 in our study were unexpectedly found in paracancerous, but not cancerous, liver tissue." (PMID 23251252, 2013). "Immunotherapy with anti-tumor cell antibodies may be improved by lenalidomide, which enhances activation of NK cells and inhibits their suppression by IL-6 and TGFβ1." (PMID 23982484, 2013). "Thus, anti-tumor functions of NK cells are suppressed by IL-6 and TGFβ1, and this is largely prevented by lenalidomide." (PMID 23982484, 2013). "To assess the possible roles of these cytokines in the suppressive activity of IMCs in the bone marrow of non-tumor-bearing mice, we added neutralizing antibodies to IL-4, IL-10 and TGFβ1 to cultures of mitogen activated T-cells co-cultured with CD11b+GR-1+ IMC." (PMID 23843936, 2013). "Thus, km23-1 can regulate fibroblast mitogenic responses through a paracrine effect of tumor cell-secreted factors such as TGFβ1, as revealed in co-culture studies." (PMID 23755307, 2013). "Tumor-exosomes can inhibit lymphocyte, predominantly CD4+ T cell proliferation in response to IL2, which is accompanied by impaired CD25 up-regulation and stronger suppressive activity of regulatory T cells (Treg), possibly due to exosome-associated TGFβ1." (PMID 23190502, 2012). "However, apoptotic tumor cells were found to release membrane-bound TGFβ1; and others have noted that the surface TGFβ1 from cancer-derived exosomes can initiate Smad signaling." (PMID 22844446, 2012). "For instance, not only the low concentration of circulating TGFβ1, but also the alteration of its signaling pathway, may concur in tumor development and progression." (PMID 22848630, 2012). "Surprisingly while TPA-induced inflammation was exaggerated in Tgfb1+/− skin, tumors formed in Tgfb1+/+ mice had increased tumor inflammation, and this was paralleled by elevated proinflammatory cytokine expression in v-RasHa-transduced Tgfb1+/+ keratinocytes compared to Tgfb1+/− keratinocytes." (PMID 23326666, 2012). "As TGFβ1 was hard to detect in xenograft tumor, the expression level of pro-TGFβ1 was presented." (PMID 22808247, 2012). "This apparent conversion in TGFβ1 function after tumor initiation is known as the “TGFβ1 paradox”." (PMID 23185371, 2012). "Tumor-exosomes may also suppress an antigen-specific response by inducing TGFβ1 and IL4 secretion and inhibiting DC maturation in draining lymph nodes." (PMID 23190502, 2012). "TGFβ1 can initiate EMT, and EMT is a hallmark of tumour invasion and metastasis." (PMID 22045191, 2012). "From these data, we hypothesise that the tumour microenvironment elicits TGFβ1 and stimulates a miRNA gene expression program that induces resistance to anti-EGFR therapy and drives lung tumour cells to EMT, invasion, and metastasis." (PMID 22045191, 2012). "TGFβ-1, in line with cancer stem cells concept, induces an increase of colonies formation in soft agar experiments and the volume of tumours was significantly larger than that of untreated LC31 cell line confirming that EMT phenotype not only promoted stemness phenotype but also the tumorigenicity." (PMID 21738704, 2011). "In order to test whether TGFβ-1 treatment succeeded in altering the tumour-initiating frequency of transformed cells, we injected EMT-LC31 cells and corresponding cell line into immunodeficient hosts." (PMID 21738704, 2011). "TGFβ1-induced inflammation may override its tumor suppressive effect at early stages during carcinogenesis." (PMID 24212650, 2011). "However, on advanced stages of tumors, TGFβ1 behaves as a tumor promoter, due to its capability to enhance angiogenesis, epithelial-to-mesenchymal transition, cell motility, and metastasis." (PMID 21845215, 2011). "Importantly, TGFβ1, the most abundant and ubiquitously expressed isoform of TGFβ, is usually considered a tumor-suppressor, due to its cytostatic activity in epithelia." (PMID 21845215, 2011).
tumor (continued). "Up-regulated genes such as COL1A1, COL1A2, PGF or TGFB1, suggested an important role of these compartment in blood vessel formation, angiogenesis, permeability and invasiveness, essential functions in tumour progression." (PMID 20735813, 2010). "It was found that various anti-tumor drugs induced TGFβ1 production in tumor cells, which could increase the potential of recurrent disease." (PMID 20442777, 2010). "Common up-regulation of genes such as COL1A1, COL1A2, PGF, LRRFIP1, TMEFF2 or TGFB1 suggested an important role of this pool of cells in blood vessel formation, angiogenesis, permeability and proliferation pathways, essentials functions in tumour progression." (PMID 20735813, 2010). "Transforming growth factor beta 1 (TGF-β1) plays a prominent role in regulating a variety of cellular functions including cell migration, cell proliferation, apoptosis, differentiation, immunosuppression, inflammation, tumor-suppression, and angiogenesis." (PMID 21152098, 2010). "Transforming growth factor beta-1 (TGF-β1) has been identified as the main inducer of tumor EMT." (PMID 20672701, 2010). "Infact, the inhibition of TGFβ1 gene by the PPARγand RXR heterodimer might account for either tumor suppression or tumorpromotion." (PMID 18615188, 2008). "Paradoxically, tumor cells have been shown to overexpress TGFB1." (PMID 17848193, 2007). "Tumour TGFβ1 may also indirectly promote cancer progression by promoting tumour vascularisation and inhibiting mechanisms of immune surveillance." (PMID 16404434, 2006). "Tumour cells produce TGFβ1 and TGFβ3 as shown in the current and previous studies." (PMID 12778073, 2003). "Combined inhibition of TF and TGFβ1 in distant fibroblast CM further suppressed migration.These findings suggest that tumour-derived influences may extend beyond the immediate TME, inducing a CAF-like, procoagulant phenotype in fibroblasts from histologically normal breast tissue." (PMID 41653379, 2026). "Additionally, tip‐cell‐derived TGFβ1 may further stimulate tumour aggressiveness, highlighting a reciprocal interaction that contributes to early tumour progression." (PMID 41431249, 2025). "These gene-positive macrophages secreted factors such as TNF, TGFB1, and notably MIF, which is implicated in T cell suppression—suggesting a complex role of these macrophages in both propagating tumor growth as well as modulating the immune landscape to favor tumor immune escape." (PMID 40620715, 2025). "The interaction between AHNAK2 and TGFB1 could potentially contribute to the establishment of an immunosuppressive microenvironment, facilitating tumor progression and highlighting AHNAK2 as a potential target for cancer-related research and therapeutic interventions." (PMID 41465903, 2025). "Consequently, pre‐treating the tumor with anti-TGFβ1 agents could potentially prevent this cell cycle arrest effect before applying MAL-PDT, as a strategy to overcome resistance." (PMID 40384860, 2025). "Therefore, CUDC‐907 could be considered a treatment strategy for TGFβ1‐induced lung and tumor fibrosis." (PMID 39083441, 2025). "Thus, it is suggested that the regulation of PLVAP expression on ECs may be related to the secretion of TGFβ1 by tumour cells." (PMID 41431249, 2025). "Furthermore, after sorting different cell populations from the TME of 4T1 tumors, we also found that, apart from the tumor cells themselves, Tgfb1 expression was also induced in monocytic MDSC (Mo-MDSC), TAM2, and CAF populations following treatment with CDDP and CDDP-Eri." (PMID 40590231, 2025). "Interestingly, TGFβ-1 exhibited differential expression patterns in the tumor and spleen tissues." (PMID 40104170, 2025). "Genes such as COL1A2, VIM, and TGFB1/TGFB4, which are associated with tumor cell invasiveness and tissue remodeling, were not only expressed in infiltrative tumor cells but also broadly present in the surrounding peritumoral tissues influenced by the tumor milieu." (PMID 40725477, 2025).
tumor (continued). "Here, we provide a possible explanation for this phenomenon: the elevated baseline level of intracellular ROS in CECs educated with tumor-derived EVs may contribute to constitutive NF-κB activation, thereby resulting in persistent upregulation of TGFβ1 expression." (PMID 38688896, 2024). "Additionally, as the malignant tumor phenotype was attenuated by disitertide and enhanced by Tgfb1, CECs from NAT exhibited corresponding decreases and increases, respectively, in the mtDNA copy number; coexpression of Nd1, Cytb, and Cox1; mitochondrial ROS level; and endogenous Tgfb1 mRNA content." (PMID 38688896, 2024). "Additionally, treatment with TGFβ pushes mouse WT and tumour organoids towards a RevSC phenotype, while organoids co-cultured with mesenchymal cells pre-treated with TGFβ1 exhibit higher expression of RevSC genes, including Clu, compared to organoids co-cultured with vehicle pre-treated mesenchyme." (PMID 38319453, 2024). "Besides, exogenous TGFβ1 administration contributed to enhanced tumor malignancy." (PMID 38688896, 2024). "Furthermore, in specimens from vitamin D3-deficient patients, we observed an inverse association between CAF tumoral infiltration and CYP24A1 levels, while CAF infiltration was positively associated with tumor OPN levels (assessed similarly to β-catenin and TGFβ1)." (PMID 38360633, 2024). "Notably, upon intercellular communication through CM-FHC, TGFβ1 depletion in EV-educated FHC cells significantly inhibited tumor cell proliferation, migration, and invasion, while re-expression of rTGFβ1 in FHC cells fully restored the enhanced malignancy of CC cells." (PMID 38688896, 2024). "Given that it was initially suggested that the subcellular location of NDRG1, p-NDRG1 (Ser330, Thr346) could determine its pleiotropic effect in tumor cells 11, we questioned if TGFβ1 drives changes in the subcellular localization of NDRG1 and p-NDRG1 (Thr346)." (PMID 36594086, 2023). "Hypothesizing that CAFs foster the niche by enriching the pro-tumor factors, an evidence-based study illustrated that an enhanced expression of TGFβ1 in a CAF-conditioned medium (CAF-CM) remained fundamental to the mesenchymal transformation of the non-CSC bladder cancer cells." (PMID 36793444, 2023). "Consequently, the unique upregulation of TGF‐beta family genes TGFB1, TGFBR2, TGFBI, TGFB1I1, and TGFB3 in S‐ECM could be due to increased production of TGF‐beta by CAFs in the tumor microenvironment." (PMID 36637997, 2023). "Additionally, tumor cells expressed Bmp2 and low levels of Gdf11, Bmp4, and Tgfb1." (PMID 38304252, 2023). "Additionally, thrombospondin 1 (THBS1), an oncogene in OSCC, is a tumor-specific ECM protein that is induced by TGFB1 and promotes cancer-cell migration while stimulating MMPs partly through integrin signaling expression, which facilitates the invasion of OSCC." (PMID 37686118, 2023). "As TGFβ1 has been implicated in promoting epithelial-to-mesenchymal transition (EMT) in tumor cells and the growth of CAF within the tumor microenvironment, elevated TGFβ stores within the ECM may impact both the proliferating tumor cells and developing CAF populations." (PMID 37296891, 2023). "Therefore, we proposed that tumor cells-derived transforming growth factor-β1 (TGFβ1) may be involved in FAM3C up-regulation in neutrophils." (PMID 37056931, 2023). "Additionally, 9 more murine immune checkpoints equivalent to human immune checkpoints documented in the TISIDB (tumor-immune system interactions and drug bank database) platform were upregulated in D374Y tumors, including TGFβ1 which plays a major role in tumor immune evasion." (PMID 36588164, 2023). "However, an increase in TGFβ1 has been observed in early cachexia in LLC-tumor bearing mice." (PMID 37701438, 2023).
tumor (continued). "Moreover, when looking at the broader cellular context, lymphocytes from clusters 7 and 28 expressed significant TGFB1 and tumor clusters 3, 8, and 14 expressed substantial CSF1, which promote immunosuppressive and pro-inflammatory properties in macrophages, respectively." (PMID 36966348, 2023). "Interestingly, increased tumor stiffness promoted actA secretion in response to TGFβ1, suggesting that as fibrosis progresses and organ stiffness increases, actA secretion may be augmented to perpetuate the maladaptive profibrotic response." (PMID 36717814, 2023). "To demonstrate that TRPV1 blockade might enable the manipulation of tumor stroma via suppressing HSF1-mediated TGFβ1 upregulation, we thus firstly investigated the influence of TRPV1 blockade on HSF1 distribution in the PANC02 tumor cells upon hyperthermia using immunofluorescence staining." (PMID 37120615, 2023). "Tumor cellular assays, qRT-PCR, western blot, ChIP, luciferase assays and CRISPR-Cas9 editing methods were performed to mechanistically understand the cooperation of GATA2 with SMAD4 in promoting TGFβ1 and AR signaling and mediating inherited PCa risk and progression." (PMID 37550764, 2023). "COMT also interacts with the pro-inflammatory cytokine tumor necrosis factor and with the tumor growth factor β1 (TGFβ1) that can modulate expression/activation of other growth factors, such as interferon gamma and tumor necrosis factor alpha, and is frequently up-regulated in tumor cells." (PMID 36827167, 2023). "Finally, we propose a therapeutic alternative for TNBC patients, whose overexpression of NDRG1 is associated with poorer survival and TGFβ1 status, by the combination of TGFβ and GSK3β inhibitors to potentially preventing tumor progression, recurrence, and chemoresistance." (PMID 36594086, 2023). "In a study on lung adenocarcinoma patients, PDPN + CAFs showed higher expression of TGFB1 and were associated with CD204 + TAM infiltration in stage I lung squamous cell cancer (SqCC), suggesting that PDPN + CAFs were associated with an immunosuppressive tumour microenvironment." (PMID 36653841, 2023). "However, it may be assumed that methylation of the promoter region silencing TGFB1 expression promotes the invasion of blood vessels by the tumor." (PMID 35798776, 2022). "In addition to killer proteins, NK cell-derived Exos may also carry tumor suppressor miRNAs such as miR-186, and thus inhibiting tumor growth and TGFβ1-dependent immune escape, and all of which exhibited the therapeutic potential of NK cell-derived Exos." (PMID 36733388, 2022). "The following parameters were analyzed in vivo using MRI or ex vivo on tissue and blood specimens: tumor growth, survival, cerebral perfusion, cellular density, tissue redox state, expression of tumor-associated NADH oxidase (tNOX) and transforming growth factor-beta 1 (TGF-β1)." (PMID 35158753, 2022). "Consequently, MT1X’s connection with TGFB1 may contribute to the malignant behavior of ccRCC tumor cells." (PMID 36149322, 2022). "However, the exact molecular mechanisms underlying TAMs' functions in promoting GSC maintenance and GSC-driven tumor growth remain largely unknown, except for a few studies reporting molecules, e.g., TGFβ1 18 and PTN 27 were specifically involved." (PMID 35673564, 2022). "In addition, selective inhibition of TGFB1 may alter resistance to anti-PD-1 therapy by altering the tumor immune environment." (PMID 36059510, 2022). "The combination of multiple cytokines may have a greater tumor-promoting effect than a single cytokine; for example, TGFβ1 leads to demethylation of PD-L1 promoter and TNFα leads to the expression of demethylated promoter and co-induces the overexpression of PD-L1." (PMID 35582541, 2022). "Furthermore, exosomes may transfer transforming growth factor beta 1 (TGFβ1), an immunosuppressive cytokine, and programmed death-ligand-1 (PD-L1), a lymphocyte activation inhibitor, to tumour cells." (PMID 36329884, 2022).
tumor (continued). "As TGFβ1 is one of the most effective immune suppressors during tumorigenesis and tumor development, it is possible that CPs could relieve immune suppression in the tumor microenvironment and activate antitumor immune reactions." (PMID 36209170, 2022). "Moreover, the TGFβ1-pSMAD2/3 pathway significantly regulates the EMT of tumour cells." (PMID 35186724, 2022). "Finally, tumor-derived PGE2 mediates indirect immunosuppressive effects by an EP2- and EP4-elicited, ERK-dependent mechanism whereby tumor-infiltrating MDSCs are activated to produce increase levels of TGFB1, culminating with NK cell dysfunction in both human and mouse experimental systems." (PMID 36319998, 2022). "Since the CD45- population from isolated B16 tumors demonstrated lower protein expression of TGFβ1 and TGFβ3 compared to tumor-infiltrating Ly6C+ high monocytes, we focused on characterizing the isoform-specific expression of TGFβ on tumor-infiltrating lymphoid and myeloid immune cells." (PMID 34789823, 2021). "Thus, we could speculate that the SLC-based signature might also be useful to predict the effect of immunotherapy and SLC members were potential downstream targets that mediated the effect of TGFβ1 on tumor immune response." (PMID 34977043, 2021). "While TGFβ1 is thought to be the primary isoform expressed in the immune system, our data suggest that TGFβ1 and TGFβ3 are both highly detectable in the tumor microenvironment and may play alternate roles in regulating T cell biology, thus offering alternate targets for anti-cancer therapy." (PMID 34789823, 2021). "Interestingly, MC-38 tumor cells deficient in Tgfβ1 production produced no experimental metastasis irrespective of target tissue (data not shown)." (PMID 34868988, 2021). "However, TGFB1 can also act as a tumor promotor during later stages of tumor development." (PMID 34771552, 2021). "Moreover, we evaluated the expression of genes that showed significant correlation with PMEPA1 in tumor cells, CAFs, and TAMs, which showed the PMEPA1 was mainly expressed in tumor cells and CAFs, TGFB1 was expressed in all three cells, and most of the chemokines were highly expressed in TAMs." (PMID 34777336, 2021). "As we know, TGFβ1 plays a key role in triggering PI3K/AKT and Raf/MEK/ERK signaling pathways, and we found that TIPE2 overexpression could reduce TGFβ1 secretion from AsPC-1 cells, and similarly decreased the protein level of TGFβ1 in tumor tissues of tumor-bearing mice." (PMID 34249724, 2021). "This may be the result of the lower abundance of TGFB1 transcripts in this tumor." (PMID 35028614, 2021). "Interestingly, and in contrast to the iCAF/myCAF classification, CD105+/ CD105- CAFs remained ‘locked’ in their initial state during long term mono-culture and, also, in response to treatment with TGFβ1 or incubation with tumour cell-conditioned medium or in tumour cell co-culture." (PMID 34638468, 2021). "The effect TGFβ1 may differ by tumor types, either by inhibiting or promoting tumor growth." (PMID 34095135, 2021). "Therefore, during the early stage of tumorigenesis, CAF PPARβ/δ may stimulate LRG1 expression, which interferes with TGFβ1-dependent redox homeostasis, to support a sustained oncogenic transformation in the surrounding tumor epithelium." (PMID 33946986, 2021). "Therefore, we inferred that TIPE2 might promote T cell activation to exert anti-tumor effect through activating DCs in a TGFβ1 dependent manner." (PMID 34249724, 2021). "Therefore, we speculated that TIPE2 may play an anti-tumor role through inhibiting TGFβ1 in tumor microenvironment." (PMID 34249724, 2021). "In consideration of the remarkably positive association between TGFB1 and PMEPA1, we could infer that the TGFbeta produced by the tumor cells, CAFs, and TAMs could induce PMEPA1 in tumor cells and CAFs and at the same time attract macrophages and inhibit T cells." (PMID 34777336, 2021). "This suggests that TGFβ1 signaling may control tumor growth." (PMID 34095135, 2021).